COG3 (component of oligomeric golgi complex 3)
Description:
Involved in ER-Golgi transport. Also involved in retrograde (Golgi to ER) transport.
Synonyms: SEC34; CDG2BB
Tractability: Antibody: UniProt places it where antibodies can reach, with high confidence; its Gene Ontology location is reachable by antibodies, with high confidence; the Human Protein Atlas places it where antibodies can reach. PROTAC: ubiquitination databases record sites on it; its protein half-life has been measured.
Target class: Other cytosolic protein
Gene: Protein-coding gene on chromosome 13 (45,464,898 to 45,536,701, forward strand). Ensembl gene ENSG00000136152.
Subcellular location: Golgi apparatus, Golgi stack membrane
Subcellular location (Human Protein Atlas): Golgi apparatus; Plasma membrane; Cytosol; Nucleoplasm
Pathways (Reactome):
Vesicle-mediated transport: COPI-mediated anterograde transport; Intra-Golgi traffic; Retrograde transport at the Trans-Golgi-Network
Gene Ontology:
Molecular function: protein binding; cargo adaptor activity
Biological process: endoplasmic reticulum to Golgi vesicle-mediated transport; glycoprotein biosynthetic process; Golgi organization; intra-Golgi vesicle-mediated transport; protein localization to organelle; protein stabilization; retrograde transport, vesicle recycling within Golgi; retrograde vesicle-mediated transport, Golgi to endoplasmic reticulum; intracellular protein transport
Cellular component: cytosol; Golgi apparatus; Golgi transport complex; plasma membrane; Golgi membrane; trans-Golgi network membrane; cis-Golgi network; Golgi cisterna membrane; membrane
Genetic constraint (gnomAD): Loss-of-function variants: 11 observed, 58 expected, observed/expected ratio (o/e) 0.19, 90% interval 0.12 to 0.31. The upper end of that interval is the gene's LOEUF score, 0.31, which puts it in group 1 of 6, group 1 being the genes least tolerant of losing a copy. Missense variants: 468 observed, 592.2 expected, observed/expected ratio (o/e) 0.79, 90% interval 0.73 to 0.85. Synonymous variants: 226 observed, 236.51 expected, observed/expected ratio (o/e) 0.96, 90% interval 0.86 to 1.07.
Gene-disease validity (ClinGen):
ClinGen rates the evidence that COG3 causes each of these diseases.
congenital disorder of glycosylation (autosomal recessive): Limited. Congenital disorder of glycosylation (CDG) is a fast growing group of inborn errors of metabolism characterized by defective activity of enzymes that participate in glycosylation (modification of proteins and other macromolecules by adding and processing of oligosaccharide side chains).
Homologues: Orthologues: chimpanzee COG3 (99% identical), macaque COG3 (99% identical), rabbit COG3 (96% identical), mouse Cog3 (96% identical), rat Cog3 (95% identical), dog COG3 (95% identical), guinea pig COG3 (93% identical), pig COG3 (91% identical), tropical clawed frog cog3 (82% identical), zebrafish cog3 (77% identical), Drosophila melanogaster Cog3 (43% identical), Caenorhabditis elegans cogc-3 (30% identical).
Diseases named in the same sentence as COG3 in open-access papers:
COG3 is named in the same sentence as 14 diseases in open-access papers, as found by Europe PMC text mining. Sharing a sentence is not in itself a finding about the gene and the disease. The quoted sentences say what the papers report.
glioblastoma (1 paper, 2019). The most malignant astrocytic tumor (WHO grade IV). "We expressed COG3 in its unedited (uned) or edited (ed) versions in three different glioblastoma cell lines (A172, U87-MG, and U118-MG), and cell proliferation and migration were tested." (PMID 30760294, 2019). "Our study further expands this observation and provides evidence that the specific RNA editing event within the COG3 I/V site, particularly enriched in malignant gliomas, is pro-tumoral in glioblastoma cells boosting both proliferation and migration." (PMID 30760294, 2019).
cancer (6 papers, 2019 to 2023). A tumor composed of atypical neoplastic, often pleomorphic cells that invade other tissues. "This recoding event, often associated with COG3 editing as in our case, provide an increase in protein stability, and a stronger affinity to antizyme, thereby facilitating entry into cell cycle, that in the case of cancer increase the malignancy." (PMID 37279397, 2023). "For instance, the Greedy Decision Forest selected a module comprising of three genes for the cancer type experiment, namely COG1, COG3, and COG5." (PMID 36207536, 2022). "A few recoding sites are highly edited in GBM compared to the normal brain with the top positions being COG3 I/V and CADPS E/G (with > 15% editing increase in cancer)." (PMID 30760294, 2019). "A recent pan-cancer study identified an appreciable number of RNA editing sites with potential clinical implications (AZIN1, COG3, and GRIA2)." (PMID 30760294, 2019). "Despite the global editing loss observed in GBM, we found that a few recoding sites (12 sites) were over-edited in cancer, with the top sites being CADPS E/G (+ 17% Δ medians) and COG3 I/V (+ 17% Δ median)." (PMID 30760294, 2019). "Furthermore, by resorting to several recent review articles, there were 26 RESs with cancer‐related clinical significance that were covered by our dataset, which resided in 7 genes (AZIN1, BLCAP, COG3, COPA, FLNB, GRIA2, and NEIL1)." (PMID 34319007, 2021).
tumor (4 papers, 2012 to 2021). "The highest mRNA expression of COG2 was found in tumour grade 2, and the mRNA expression of COG3 was only associated with grade 3." (PMID 34539936, 2021). "Previously reported editing events in GRIA2, AZIN1, and COG3 are thought to promote adult tumor progression based on functional cell viability assays." (PMID 34789196, 2021). "Recently, in a study carried out at both genomic and transcriptional levels, SRP9 and COG3 mRNA expressed in tumor cells were clearly shown to carry SBS that were conflicting with the genome sequence." (PMID 23137041, 2012). "These variations affected the following genes: AZIN1 (c.A1099G), COG3 (c.A1903G), COPA (c.A490G), GATAD2A (c.A65G), GLT8D1 (c.C955G) and SLC25A39 (c.C809T), and were all verified by Sanger sequencing on tumors and non-tumor DNA." (PMID 33963205, 2021). "Intriguingly, in the case of COG3, a thymine (in tumor DNA) was replaced by a cytidine (in tumor RNA) which cannot be carried out by ADAR nor APOBEC enzymes because APOBEC converts cytosine to uracile in RNA sequences." (PMID 23137041, 2012). "Similarly, high mRNA expression of 5 of all COG isoforms (COG2, COG3, COG5, COG6, COG7, and COG8) was also correlated with favourable OS of KIRC patients with tumour grade 2, grade 3, and grade 4, while patients with low mRNA expression of COG4 showed higher survival rate." (PMID 34539936, 2021).
infection (2 papers, 2024 to 2025). The state of being infected such as from the introduction of a foreign agent such as serum, vaccine, antigenic substance or organism. "Moreover, infection with wild-type C. trachomatis L2 (CTL2) was significantly reduced in COG3-deficient cells, while a much more modest reduction was observed for C. trachomatis serovar E (CTE), known to invade cells in a less HSPG-dependent manner." (PMID 40794560, 2025).
COG3 also shares sentences with these, for which no sentence is quoted: acute myeloid leukemia (1 paper); Cerebellar atrophy (1); Failure to thrive (1); hypoceruloplasminemia (1); keratosis pilaris (1); malignant glioma (1); microcephaly (1); primordial dwarfism (1); renal clear cell carcinoma (1); schizophrenia (1).